TRAJ42 (T cell receptor alpha joining 42)
Description:
J region of the variable domain of T cell receptor (TR) alpha chain that participates in the antigen recognition. Alpha-beta T cell receptors are antigen specific receptors which are essential to the immune response and are present on the cell surface of T lymphocytes. Recognize peptide-major histocompatibility (MH) (pMH) complexes that are displayed by antigen presenting cells (APC), a prerequisite for efficient T cell adaptive immunity against pathogens. Binding of alpha-beta TR to pMH complex initiates TR-CD3 clustering on the cell surface and intracellular activation of LCK that phosphorylates the ITAM motifs of CD3G, CD3D, CD3E and CD247 enabling the recruitment of ZAP70. In turn, ZAP70 phosphorylates LAT, which recruits numerous signaling molecules to form the LAT signalosome. The LAT signalosome propagates signal branching to three major signaling pathways, the calcium, the mitogen-activated protein kinase (MAPK) kinase and the nuclear factor NF-kappa-B (NF-kB) pathways, leading to the mobilization of transcription factors that are critical for gene expression and essential for T cell growth and differentiation. The T cell repertoire is generated in the thymus, by V-(D)-J rearrangement. This repertoire is then shaped by intrathymic selection events to generate a peripheral T cell pool of self-MH restricted, non-autoaggressive T cells. Post-thymic interaction of alpha-beta TR with the pMH complexes shapes TR structural and functional avidity.
Gene: T-cell receptor joining (J) gene on chromosome 14 (22,496,887 to 22,496,952, forward strand). Ensembl gene ENSG00000211847.
Subcellular location: Cell membrane
Gene Ontology:
Cellular component: plasma membrane
Diseases named in the same sentence as TRAJ42 in open-access papers:
TRAJ42 is named in the same sentence as 4 diseases in open-access papers, as found by Europe PMC text mining. Sharing a sentence is not in itself a finding about the gene and the disease. The quoted sentences say what the papers report.
primary biliary cholangitis (1 paper, 2025). Primary biliary cholangitis (PBC) is a chronic and slowly progressive cholestatic liver disease of autoimmune etiology characterized by injury of the intrahepatic bile ducts that may eventually lead to liver failure. "For the α chain, Trav10 [S26], Trav16n [S20,26], Trav17 [S27], Trav5‐4 [S26], Traj42 [S20,26] and Traj53 [S26] were associated with Type I diabetes, whereas Trav12‐2 [S28] was associated with primary biliary cholangitis." (PMID 40665793, 2025).
cancer (1 paper, 2025). A tumor composed of atypical neoplastic, often pleomorphic cells that invade other tissues. "TCR sequencing of MR1-restricted cancer-activated T cells showed that the majority of these cells shared a conserved 10-amino acid–long TCR-α chain motif as a result of TRAJ42 use." (PMID 39744940, 2025). "TCR sequencing of the cancer-reactive T cell populations in these lines revealed recurrence of TRAJ42 use, thereby generating unusually long CDR3-α (16 or 17 amino acids) incorporating a 10 amino conserved TCR-α chain motif." (PMID 39744940, 2025). "A similar conservation of TCR-α sequence, including a conserved Y95-α residue, is seen in MAIT cells, and suggests that TRAJ42+ cancer-activated invariant T cells are likely to see a common ligand." (PMID 39744940, 2025). "TRAJ42 was paired with 6 different TRAV genes within the cancer activated MR1-restricted T cell population." (PMID 39744940, 2025). "The bias toward TRAJ42 use and conservation of a semi-invariant motif makes it tempting to speculate that the cells we describe across multiple donors likely exhibit limited antigen diversity and might bind to an identical MR1-bound cargo at the cancer cell surface." (PMID 39744940, 2025).
TRAJ42 also shares sentences with these, for which no sentence is quoted: COVID-19 (1 paper); Type I diabetes (1).